TNF (tumor necrosis factor)
Diseases named in the same sentence as TNF in open-access papers (continued):
Sharing a sentence is not in itself a finding about the gene and the disease.
cancer (continued). "Furthermore, chronic gastric inflammation is an important factor in promoting GIM and cancer progression, and IL-6, TNF-α, and IL-1β are characteristic cytokines involved in the inflammatory response." (PMID 38096029, 2023). "Accordingly, an ensemble learning model could uncover more precise targets within the NFκB/TNF signaling pathway for cancer therapy." (PMID 37475016, 2023). "Identifying the means to sensitise the cancer cells to TNFα would have therapeutical benefits." (PMID 36900285, 2023). "Mounting evidence from large retrospective studies shows no increased risk of relapse (or new cancer) with anti-TNF therapies or thiopurines, nor with vedolizumab or ustekinumab." (PMID 37674502, 2023). "Kyoto Encyclopedia of Genes and Genomes (KEGG) pathway enrichment analysis showed that BLACAT3 knockdown could activate several cancer-related signaling pathways including the TNF/NF-κB signaling pathway." (PMID 37612524, 2023). "The authors stimulated ILC1s from patients with PMA/ionomycin and cultured them with CLL cells and ILC1s were unable to enhance IFN-γ or TNF production showing a defect in responsiveness of ILCs from cancer patients which suggests an immunosuppressive role for ILC1s in certain cancer environments." (PMID 38567059, 2023). "Moreover, tumor necrosis factor (TNF) plays an important role in apoptosis, inflammation, and immunity, and plays a vital role in the pathogenesis of many diseases, including cancer." (PMID 37455914, 2023). "Through key components such as Oleanolic acid, Butin, β-sitosterol, Stigmasterol, and Enoxolone and other components interferes with AKT1, IL-6 and TNF, and regulates pathway in cancer, PI3K-AKt signaling pathway and MAPK pathway to play a therapeutic role in hepatitis E." (PMID 37035802, 2023). "In addition, Cx43 mediates the transfer of cGAMP from brain metastatic cancer cells to astrocytes inducing the release of factors (such as TNFα) that activate the NF-kB pathways on cancer cells, thus promoting metastasis progression." (PMID 38293652, 2023). "Moreover, TNF-alpha altering the microenvironment increased tumour invasiveness and promoted cancer metastasis." (PMID 37753372, 2023). "The top Cancer Hallmark pathways enriched in the SI rats, compared with the group-housed rats, included IFNα, IFNγ, and inflammatory responses, and IL6/JAK/STAT3 and TNFα signaling via NFκB." (PMID 36980301, 2023). "The secretome of cancer cells and soluble agents such TNFα contribute to resistance to treatments." (PMID 37046676, 2023). "TNF-α can therefore act either as a pro-tumoral cytokine, favouring cell proliferation, cell migration, angiogenesis, and diseases progression in a number of cancer types, or as an anti-tumorigenic biomolecule." (PMID 36980727, 2023). "It is noteworthy that the duration of anti-TNFα treatment did not seem to affect the risk of incident cancer or its type and its recurrence risk." (PMID 36672491, 2023). "This systematic review aims to assess whether the cytokines IL-6, IL-8 and TNF-α are potential salivary biomarkers that allow early diagnosis of cancer." (PMID 37099710, 2023). "Additionally, the activation of TLR4 by Hsp70/90 Evs has also been found to be responsible for the systemic rise in the levels of inflammatory cytokines, including TNF-α and IL-6, during cancer cachexia." (PMID 37998333, 2023). "In addition, lymphocytes secrete cytokines, such as interferon-γ and TNF-α, which regulate cancer cell growth and metastasis through cellular and humoral immune mechanisms." (PMID 36719281, 2023). "Because TNF-α signaling may modulate the course of cancer, it can be therapeutically targeted to ameliorate clinical outcomes." (PMID 36765695, 2023). "M1-M2 macrophages produce a high quantity of inflammatory cytokines such as IL-1, IL-6, and TNF-alpha that in turn stimulate the further recruitment of other macrophages and concomitantly increase the aspecific response in site of the adaptive anti-cancer immune response." (PMID 36900413, 2023).
cancer (continued). "Furthermore, SyA treatment significantly reduced the levels of cancer promoting proinflammatory cytokines TNF, IL-2, IL-6, and IL-10 in ovarian cancer cells." (PMID 37259418, 2023). "On the other hand, studies on the ethanolic extract of ginger (Zingiber officinale) have revealed that it may act as an anti-cancer and anti-inflammatory agent by inhibiting NF-кB activation through suppressing pro-inflammatory cytokine, TNF-α." (PMID 36771154, 2023). "During cancer surgery, the effect of VAs on the TNF-α release is still uncertain." (PMID 36765695, 2023). "Inflammation is fundamentally mediated by TNF-α, which also promotes the growth of cancers." (PMID 37446321, 2023). "As reported, M1 macrophages hinder cancer progression via producing pro-inflammatory mediators (tumor necrosis factor-alpha and interleukin-1), while M2 macrophages advance cancer progression by means of anti-inflammatory cytokine secretion (chemokine 17, chemokine 22, and interleukin-10)." (PMID 37160813, 2023). "Cancer patients on Doxorubicin and Cyclophosphamide treatment were proven to have elevated levels of free radicals leading to overproduction of inflammatory mediators as Interleukin-1β (IL-1β) and tumor necrosis factor-alpha (TNF-α)." (PMID 37140732, 2023). "Inhibition of TNFα also aids in the suppression of various carcinomas." (PMID 36996146, 2023). "TNF-alpha clearly plays a major role in establishing a link between inflammation and cancer." (PMID 35186129, 2022). "On the other hand, the increased levels of MCP-1 and TNFα could also reflect a general bystander immune activation initiated by the cancer treatment." (PMID 35164829, 2022). "TNF induces cell survival, apoptosis, and necrosis, and is widely expressed in cancer." (PMID 36016607, 2022). "Although the local inflammation promoting cancer development remains unclear, the production of cytokine growth factors via dysbiosis—such as tumor necrosis factor—is uncertain." (PMID 35628566, 2022). "The information obtained so far regarding the roles of TNFα and its receptors in cancer has split the scientific and clinical communities between those who consider TNFα as “therapy” and those who regard the different members of the TNFα-TNFR family as “targets”." (PMID 35663982, 2022). "Other proinflammatory cytokines (TNF-alpha, IL-2, IL-12, etc.)are also of great interest as therapeutic targets for cancer that could be affected by M/A." (PMID 35158753, 2022). "Indeed, excessive ROS formation and inflammatory cytokines release (i.e., tumoral necrosis factor-alpha [TNF-α], interleukin- 6, and 1β [IL-6 and IL-1β]) are master mediators of proteolytic systems and muscle atrophy during cancer." (PMID 35847939, 2022). "It was also reported that F. nucleatum infections may cause cancer through their effect on MMP9 pathways and upregulation of cytokines such as tumor necrosis factor (TNF)-α, IL-1β, and IL-6." (PMID 35112169, 2022). "Clearly, the study explored the various potential mechanistic pathways that might explain the tumorgenesis and development of cancer through the estimation of apoptotic and inflammatory markers such as Bcl-2, Bax, IL-8 and TNF-α." (PMID 35203561, 2022). "The increase of Tumor necrosis factor alpha (TNF-α) paired increase of interleukins might be related a worst prognosis in cancer." (PMID 35241969, 2022). "Lim and colleagues found out that TNF stabilizes the expression of PDL1 on cancer cells." (PMID 35681583, 2022). "Gene expression profiling using microarray technology has been applied to identify physiologically and clinically significant subgroups of TNF-responsive tumors, elucidate the combinatorial and complex nature of cancers, and advance our mechanistic understanding of oncogenesis." (PMID 35884586, 2022).
cancer (continued). "To this end, we compared the relationships between OM grade, oral mucosal dryness, and inflammatory mediators (Interleukin (IL)-1β, IL-6, IL-10, IL-12p70, tumor necrosis factor (TNF), prostaglandin E2, and vascular endothelial growth factor) in patients with cancer and in healthy volunteers (HV)." (PMID 35476641, 2022). "In the inflammation process, pro-inflammatory cytokines such as tumor necrosis factor–α (TNF-α) and interleukin-1β (IL-1β) consequently activate transcriptional regulatory signaling pathways and cooperate to regulate cancer-related pathophysiological processes including proliferation." (PMID 35681644, 2022). "Additionally, the unique ability to prestore and release potentially beneficial anticancer mediators such as tumor necrosis factor α (TNF-α) and the granulocyte–macrophage colony-stimulating factor, mediating the necrosis of cancer cells, is prognostic." (PMID 35936682, 2022). "In fact, cytotoxic cancer therapies frequently activate tumor necrosis factor (TNF) signaling and nuclear factor kappa B (NFκB), a transcription factor that mediates the expression of hundreds of genes involved in cancer cell death and survival, inflammation, and immunity." (PMID 35625711, 2022). "However, in the present study, significant reverse correlation was found between the frequencies of CD8+IFN-γ+ (monofunctional T cells) and CD8+IFN-γ+TNF-α+ T cells (polyfunctional T cells) and higher cancer stage." (PMID 36376825, 2022). "EVs generated from NK cell membranes are enriched in FasL and TNF, making them cytotoxic to cancer." (PMID 36498469, 2022). "However, toxicities due to TNF infusion, such as fever, rigors, and pulmonary edema, limited its use in cancer treatment." (PMID 35936003, 2022). "In this study, TNFα enhances the self-renewal abilities of the cancer cells." (PMID 36276076, 2022). "TNF-α is important for cancer cell extravasation and intravasation during metastasis." (PMID 35385679, 2022). "The cause of such discrepancy is still unknown but further studies are needed to determine in which cancers the TNF-α status can or cannot be a reliable prognostic/response marker." (PMID 35406442, 2022). "Several studies have suggested that IFs are related to the development and prognosis of cancer, among which TNF-α and IL-6 are the most typical cytokines related to inflammation, which can play an important role in host defense by regulating immune and inflammatory responses." (PMID 36284990, 2022). "Consequently, emerging evidence and recent clinical trials suggest that TNF inhibitors are safe and beneficial in the treatment of patients with cancer and irAEs." (PMID 36016934, 2022). "It has also been reported that TNF-α upregulates PD-L1 expression in cancer cells." (PMID 36185255, 2022). "Taken together, the findings obtained so far suggest that when the TNFα-TNFR network is considered in cancer therapy, the “target” approach may apply better than the “therapy” tactic." (PMID 35663982, 2022). "However, stimulation of the cancer cells with LPS markedly increased TNFα levels in the culture medium." (PMID 36119107, 2022). "In trying to understand the opposing observations on TNFα in cancer, it is important to consider that the TNFα-TNFR network includes many different members, generating intricate interactions that are spatially and temporally regulated, leading to diverse consequences under different conditions." (PMID 35663982, 2022). "Accordingly, TNF was gradually viewed as a target for cancer treatment." (PMID 35844550, 2022). "In addition, ICT can promote tumor necrosis factor-α so as to promote the apoptosis of cancer cells." (PMID 35387305, 2022). "Therefore, use of antibiotics that kill microbiome to reduce the levels of LPS and TNFα together with an IAP antagonist for cancer therapy should be avoided." (PMID 36119107, 2022). "The TNFα/NFκB signaling pathway might play a critical role in the development of the proinflammatory condition in many cancers." (PMID 35563222, 2022).
cancer (continued). "Recent studies demonstrated that oncolytic adenoviruses could upregulate TNF‐α production, resulting in cancer cell apoptosis and necrosis." (PMID 35762456, 2022). "The essential innate immunity effector cells, natural killer and dendritic cells, express multiple plasma membrane-associated tumor necrosis factor (TNF) superfamily (TNFSF) ligands that, through simultaneous and synergistic engagement, mediate anti-cancer cytotoxicity." (PMID 35392082, 2022). "Given that TNF, also known as cachexia factor, is considered an important mediator of central nervous system inflammation during cancer cachexia, this brain–fat axis may be involved in adipose tissue remodeling and emaciation observed during cancer cachexia." (PMID 36105371, 2022). "Therefore, there is potential for sensitising cancer cells to TNF-induced cell death, but greater understanding of how its functions vary is needed." (PMID 35401556, 2022). "TNF-α driven upregulation of mitochondrial reactive oxygen species production as well as diminished antioxidant presence in muscle cells also contribute to the high levels of oxidative stress present in cancer patients." (PMID 36422360, 2022). "In this context, the pro-inflammatory cytokines, tumor necrosis factor-α (TNF-α) and interleukin (IL)-6 (a major inducer of CRP), as well as the immunosuppressive cytokine, IL-10, have all been implicated in both the initiation and development of cancer." (PMID 35223501, 2022). "Moreover, TNF-α is involved in biological processes, including cell proliferation, differentiation, apoptosis, lipid metabolism, and coagulation in cancer." (PMID 36233348, 2022). "Up-regulation of cytokines in the bone microenvironment may contribute to peripheral and central components of cancer-induced bone pain, as osteoclasts are derived from monocyte/macrophage hematopoietic lineage and express receptors for TNFα and IL-6." (PMID 35335997, 2022). "Therefore, in cancer cells, pro-inflammatory cytokines such as IL-1β and TNF-α can only increase the stability of CXCL1 mRNA." (PMID 35054978, 2022). "The source genes found in the signaling pathways, such as the transcriptional mis-regulation in cancer, TNF signaling pathway, T cell receptor signaling pathway, PI3KAkt signaling pathway, and lysine degradation, were evaluated in the top-20 statistically enriched pathways (p < 0.05)." (PMID 36553452, 2022). "SSD and TNF-α have a lot of promise for cancer patients as a combination adjuvant treatment." (PMID 36547471, 2022). "More importantly, despite NK cells might express high amounts of TNFα, it is still not known whether NK cells can activate classical necroptosis in cancer cells by using TNFα." (PMID 35651603, 2022). "TNF-α has been extensively investigated as an anti-cancer agent and adjuvant." (PMID 35740607, 2022). "To gain further mechanistic insight, we explored potential signalling pathways that could mediate the effects of cardiac glycosides and ATP1A1 knockdown on immune checkpoint protein expression in TNF/IFN-ɣ-stimulated cancer cells." (PMID 35150740, 2022). "TNF signaling pathways were identified in almost all cancers by CellCallEXT." (PMID 36230879, 2022). "TNF was first discovered because of its anti-cancer activity." (PMID 39076643, 2022). "As a major tumor necrosis factor, TNF-α plays a key role in killing cancer." (PMID 36213824, 2022). "TNF is accountable for various signaling events within cells, leading to necrosis or apoptosis, therefore playing a pivotal role in the resistance to infection and cancers." (PMID 35884586, 2022).
cancer (continued). "Finally, this review will highlight the development and future of therapeutic applications which modulate the JAK-STAT or the TNF signaling pathways in cancers." (PMID 35844493, 2022). "However, since pro-TNF therapy was initially intended to treat cancer, concerns about adverse effects accompany the anti-TNF therapy." (PMID 36678712, 2022). "Thus, when manipulation of members of the TNFα-TNFR family is considered in cancer therapy, one needs to determine many aspects in a most specific manner: who are the patients who can benefit from the treatment?" (PMID 35663982, 2022). "Adipose tissue dysregulation promotes an inflammatory state in which adipocytes and immune cells release pro-inflammatory cytokines and sex hormones, such as hs-CRP, IL-6, leptin, TNF-α, estrogens, among others, increasing cell proliferation and cancer development." (PMID 35795051, 2022). "This largest nationwide study to date compared cancer risk in TNF inhibitor users to non-biologic disease-modifying anti-rheumatic drug (nbDMARD) users in Korean patients with RA." (PMID 35945635, 2022). "It remains to be seen whether TNF signalling can be harnessed to successfully treat cancer patients in the clinic because its effects are highly context-dependent." (PMID 35401556, 2022). "Moreover, early necroptotic cells with bright-green nuclei and late necroptotic cells with fragmented, orange to red nuclei were distinguished upon treatment of test cancer cell lines with the IC50 of human TNF-α protein." (PMID 35205024, 2022). "TNF is secreted from macrophages and induces cell death of certain cancer cell lines." (PMID 36438925, 2022). "Thus, we examined iNOS and TNFα production by M1 macrophages after their co-culture with OVCA cancer cells." (PMID 35205790, 2022). "A highly relevant study showed increases in the expression of TET2 and 5hmC in a number of cancers that modulated the expression of TNF-α signalling components and facilitated chemotherapy resistance in slow-cycling cancer cells by restraining proapoptotic signalling." (PMID 34905094, 2022). "TNF-α activates the NF-κB pathway, which is significantly related to cancer pain." (PMID 35719369, 2022). "Additionally, the uterine microbiome can stimulate the production of pro-inflammatory cytokines in endometrial cells, including IL-1α, IL-1β, IL-17α, and TNF-α, which are involved in the carcinogenesis of various cancers." (PMID 35628566, 2022). "TNF is known to promote the migration and invasive abilities of cancer cells." (PMID 35401557, 2022). "Furthermore, MC are innate immune cells inherent in tissues, which can promote angiogenesis and accelerate the progression of malignant tumors by releasing different chemokines (such as TNF-α and IL-1b) and inflammatory cytokines." (PMID 36247874, 2022). "On one hand, TNF-α promotes cancer cells survival by activating TNFRs, vascular cell adhesion molecule 1 (VCAM1) and altering the protein complex I and II (complex I consists of TRADD, TRAF2 and RIP and Complex II that consists of TRADD, RIP, FADD and caspase-8)." (PMID 35954156, 2022). "Our findings suggest that salivary IL-6, IL-10, and TNF levels may be used as biomarkers for OM occurrence and grade in patients with cancer." (PMID 35476641, 2022). "In addition, tumor necrosis factor-alpha (TNF-α) exerts essential biological functions in various cancers." (PMID 36532852, 2022). "TNF-α can have either anti-cancer activity or behave as an immunosuppressive cytokine." (PMID 36551577, 2022). "Strikingly, cancer cell subgroup 5, which exclusively originated from left-sided CRC, presented upregulation of several cancer-associated signaling pathways, including estrogen signaling, ErbB signaling, TNF signaling, HIF-1 signaling, and AMPK signaling." (PMID 34793335, 2022).